H4C2 (H4 clustered histone 2)
Description:
Core component of nucleosome. Nucleosomes wrap and compact DNA into chromatin, limiting DNA accessibility to the cellular machineries which require DNA as a template. Histones thereby play a central role in transcription regulation, DNA repair, DNA replication and chromosomal stability. DNA accessibility is regulated via a complex set of post-translational modifications of histones, also called histone code, and nucleosome remodeling.
Synonyms: H4/I; H4FI; HIST1H4B
Target class: Other nuclear protein
Gene: Protein-coding gene on chromosome 6 (26,025,802 to 26,027,283, reverse strand). Ensembl gene ENSG00000278705.
Subcellular location: Nucleus; Chromosome
Pathways (Reactome):
Gene expression (Transcription): B-WICH complex positively regulates rRNA expression; DNA methylation; ERCC6 (CSB) and EHMT2 (G9a) positively regulate rRNA expression; MLL4 and MLL3 complexes regulate expression of PPARG target genes in adipogenesis and hepatic steatosis; NoRC negatively regulates rRNA expression; PRC2 methylates histones and DNA; RNA Polymerase I Promoter Escape; RNA Polymerase I Promoter Opening; RUNX1 regulates genes involved in megakaryocyte differentiation and platelet function; RUNX1 regulates transcription of genes involved in differentiation of HSCs; Regulation of endogenous retroelements by KRAB-ZFP proteins; Regulation of endogenous retroelements by Piwi-interacting RNAs (piRNAs); Regulation of endogenous retroelements by the Human Silencing Hub (HUSH) complex; SIRT1 negatively regulates rRNA expression; Transcriptional regulation by small RNAs
Chromatin organization: CHD1 and CHD2 subfamily; CHD6, CHD7, CHD8, CHD9 subfamily; ChAHP complex assembly; HATs acetylate histones; HDACs deacetylate histones; HDMs demethylate histones; Interaction of NuRD complexes with transcription factors; NuRD complex assembly; PKMTs methylate histone lysines; RMTs methylate histone arginines
DNA Repair: Cleavage of the damaged purine; Cleavage of the damaged pyrimidine; Nonhomologous End-Joining (NHEJ); Processing of DNA double-strand break ends; Recognition and association of DNA glycosylase with site containing an affected purine; Recognition and association of DNA glycosylase with site containing an affected pyrimidine; Recruitment and ATM-mediated phosphorylation of repair and signaling proteins at DNA double strand breaks
Cell Cycle: Condensation of Prophase Chromosomes; Deposition of new CENPA-containing nucleosomes at the centromere; G2/M DNA damage checkpoint; Inhibition of DNA recombination at telomere; Packaging Of Telomere Ends
Developmental Biology: Activation of anterior HOX genes in hindbrain development during early embryogenesis; Chromatin modifications during the maternal to zygotic transition (MZT); Replacement of protamines by nucleosomes in the male pronucleus
and 20 more pathways
Gene Ontology:
Molecular function: protein binding; RNA binding; structural constituent of chromatin; DNA binding; protein heterodimerization activity
Biological process: negative regulation of megakaryocyte differentiation; nucleosome assembly; chromatin organization; protein localization to CENP-A containing chromatin; telomere organization
Cellular component: CENP-A containing nucleosome; chromosome, telomeric region; extracellular exosome; membrane; nucleoplasm; nucleosome; nucleus; protein-containing complex; extracellular region; chromosome
Genetic constraint (gnomAD): Loss-of-function variants: 8 observed, 5.84 expected, observed/expected ratio (o/e) 1.37, 90% interval 0.77 to 1.91. That is too few expected variants to judge how well the gene tolerates losing a copy. Missense variants: 267 observed, 157.48 expected, observed/expected ratio (o/e) 1.7, 90% interval 1.53 to 1.87. Synonymous variants: 145 observed, 58.26 expected, observed/expected ratio (o/e) 2.49.
Homologues: Orthologues: chimpanzee H4C6 (100% identical), tropical clawed frog h4c3 (100% identical). Paralogues in human: H4C1 (100% identical), H4C11 (100% identical), H4C12 (100% identical), H4C13 (100% identical), H4C14 (100% identical), H4C15 (100% identical), H4C16 (100% identical), H4C3 (100% identical), H4C4 (100% identical), H4C5 (100% identical), H4C6 (100% identical), H4C8 (100% identical), and 2 more.